SEPHS2 (selenophosphate synthetase 2)
Description:
Selenophosphate synthase that generates the selenium donor for selenocysteine biosynthesis by catalyzing formation of selenophosphate from selenide and ATP.
Synonyms: SPS2; SPS2b
Tractability: PROTAC: UniProt records ubiquitination sites on it; ubiquitination databases record sites on it; its protein half-life has been measured.
Gene: Protein-coding gene on chromosome 16 (30,443,631 to 30,445,874, reverse strand). Ensembl gene ENSG00000179918.
Subcellular location: Cytoplasm
Subcellular location (Human Protein Atlas): Nucleoplasm
Pathways (Reactome):
Metabolism: Selenocysteine synthesis
Gene Ontology:
Molecular function: protein binding; selenide, water dikinase activity; ATP binding
Biological process: selenocysteine biosynthetic process
Cellular component: cytoplasm; cytosol
Genetic constraint (gnomAD): Loss-of-function variants: 13 observed, 23.26 expected, observed/expected ratio (o/e) 0.56, 90% interval 0.36 to 0.89. The upper end of that interval is the gene's LOEUF score, 0.89, which puts it in group 3 of 6, group 1 being the genes least tolerant of losing a copy. Missense variants: 541 observed, 577.2 expected, observed/expected ratio (o/e) 0.94, 90% interval 0.87 to 1.01. Synonymous variants: 239 observed, 229.63 expected, observed/expected ratio (o/e) 1.04, 90% interval 0.94 to 1.16.
Homologues: Orthologues: mouse Sephs2 (90% identical), guinea pig SEPHS2 (90% identical), dog SEPHS2 (70% identical), zebrafish sephs3 (60% identical), Drosophila melanogaster Sps1 (58% identical), tropical clawed frog sephs3 (56% identical), Caenorhabditis elegans seld-1 (41% identical), Drosophila melanogaster Sps2 (37% identical). Paralogues in human: SEPHS1 (65% identical).
Diseases named in the same sentence as SEPHS2 in open-access papers:
SEPHS2 is named in the same sentence as 28 diseases in open-access papers, as found by Europe PMC text mining. Sharing a sentence is not in itself a finding about the gene and the disease. The quoted sentences say what the papers report.
breast carcinoma (7 papers, 2019 to 2025). "SEPHS2 protein levels are elevated in human breast cancer patient samples and loss of SEPHS2 impairs growth of orthortopic mammary tumor xenografts in mice." (PMID 36105219, 2022). "SEPHS2 is essential for the survival of cancer cells, as demonstrated by studies in which the loss of the SEPHS2 gene in breast cancer cells (MDAMB231) impaired the growth of orthotopic mammary-tumor xenografts when these cells were injected in wild-type, nude athymic mice." (PMID 36358931, 2022). "The action and regulatory mechanisms of SEPHS2 as well as its role in carcinogenesis (especially breast cancer) remain ambiguous and need further clarification." (PMID 31695102, 2019). "Bioinformatics analysis evidenced higher amplification frequencies of SEPHS2 in breast cancer than in other cancer types." (PMID 31695102, 2019). "It was shown that SEPHS2 was elevated in breast tumor samples, and its overexpression was correlated with advanced tumor grade, suggesting that SEPHS2 may serve as a prognostic marker and therapeutic target for patients with breast cancer." (PMID 37293295, 2023). "Overall, these in vivo results demonstrate that the expression of SEPHS2 and SEPSECS is less critical for mammary breast tumour growth than for breast cancer cells to survive in the bloodstream and colonise the lungs." (PMID 39433871, 2024). "Similarly, abnormal upregulation of selenium uptake and selenocysteine biosynthesis occurs in many cancer cells, including breast cancers and acute myeloid leukemia, making SEPHS2 crucial for their survival but not for normal cells." (PMID 39728918, 2024). "Therefore, because triple negative breast cancer (TNBC) is biologically the most aggressive breast cancer subtype and its treatment represents a challenge due to the absence of well-defined molecular targets, we evaluated SEPHS2 expression in two TNBC cell lines and patient samples." (PMID 31695102, 2019). "In line with the working model proposed, the deletion of SEPHS2 and SEPSECS does not affect the proliferation of TNBC cultured at high density, and a transient interference with their expression does not appreciably delay the growth of orthotopic mammary tumours." (PMID 39433871, 2024).
acute myeloid leukemia (2 papers, 2024 to 2025). Acute myeloid leukemia (AML) is a group of neoplasms arising from precursor cells committed to the myeloid cell-line differentiation. "Complementarily, a genome-wide CRISPR-Cas9 dropout screening in human acute myeloid leukemia (AML) cells identified SEPHS2, a gene critical for the selenocysteine biosynthetic pathway." (PMID 40867560, 2025).
breast tumor (2 papers, 2013 to 2023). "We also compared methylation profiles for Tamoxifen resistant genes, and identified several hypermethylation genes in breast tumors, such as ACTA1, ISG15, PTK6 and SEPHS2." (PMID 23630576, 2013).
Obesity (2 papers, 2020 to 2022). Accumulation of substantial excess body fat. "Indeed, in a recent study of animal models, a combination of hyperglycemia, long-term insulin resistance and obesity was linked to reduced mRNA expression of thioredoxin reductase 3 (Txnrd3) along with selenoprotein Gpx3 and selenophosphate synthetase 2 (Sephs2) in adipose tissue." (PMID 35328380, 2022).
selenium deficiency (2 papers, 2017 to 2025). A nutritional deficiency disease resulting from inadequate selenium levels in the body, which can lead to impaired function of selenoproteins essential for antioxidant defense and thyroid hormone metabolism. "One of these, miRNA-185, whose expression decreased under selenium deficiency, was confirmed to regulate expression of glutathione peroxidase 2 (GPx2) and selenophosphate synthetase 2 (SPS-2) genes." (PMID 29065468, 2017). "In contrast, genes associated with selenium deficiency such as HIF1 AAS3, HIF1 AAS1, HIF1 A, and SEPHS2 were upregulated." (PMID 40459789, 2025).
adenoma (1 paper, 2018). A neoplasm arising from the epithelium. "GPX2 and TXNRD3 showed a higher expression and GPX3, SELENOP, SELENOS, and SEPHS2 exhibited a lower expression in the disease tissue from adenomas and both cancer groups (p-values from 0.023 to <0.001)." (PMID 30469315, 2018). "These included increasing down-regulation of GPX3, SELENOP, SELENOS, and SEPHS2 and up-regulation of GPX2, SELENOH, and TXNRD3, in groups of normal-matched tissues, adenomas, and adenomas with HGD." (PMID 30469315, 2018).
cognitive decline (1 paper, 2025). "Furthermore, conditional analysis incorporating 22 loci associated with cognitive decline from the GWAS Catalog (selected from 455 before pruning) showed that both SEPHS2 and CLVS2 retained their original P values, indicating the robustness of our findings." (PMID 40728933, 2025). "We successfully replicated the association of SEPHS2 in both the validation dataset and our MCI cohort, establishing it as a robust gene linked to cognitive decline." (PMID 40728933, 2025). "In conclusion, we validated cognitive decline-related variants in the HOPE Cohort and identified novel genes associated with SCD, SEPHS2 and CLVS2, supported by multi-omics evidence." (PMID 40728933, 2025). "Further investigations to validate the roles of CLVS2 and SEPHS2 may provide a more comprehensive exploration of mechanisms related to cognitive decline." (PMID 40728933, 2025).
endotoxemia (1 paper, 2020). "Similar to the whole liver homogenate results, endotoxemia was associated with a decrease in the mRNA levels of Sephs2, Pstk, Sepsecs and the selenium recycler protein, Scly within the hepatocyte fraction of the liver." (PMID 33224150, 2020). "Knock-down studies of two of the factors required for Se processing that decrease after endotoxemia, selenophosphate synthetase 2 and phosphoseryl tRNA kinase, are reported to limit production of selenoproteins in vitro." (PMID 33224150, 2020). "In the lung, endotoxemia was associated with increased transcription of Sephs2, no change in Pstk or Sepsecs and increased transcription of Scly." (PMID 33224150, 2020). "However, it has been that reported endotoxemia downregulated the transcription of Pstk, Sephs2, and Selenop in both male and female mice, and we speculate the downstream impact on translation occurs in both sexes." (PMID 33224150, 2020). "Finally, in the spleen, endotoxemia was associated with no change in the transcription of Sephs2, an increase in Pstk, and no change in Sepsecs or Scly." (PMID 33224150, 2020).
epilepsy (1 paper, 2021). A brain disorder characterized by episodes of abnormally increased neuronal discharge resulting in transient episodes of sensory or motor neurological dysfunction, or psychic dysfunction. "Herein, we identified seven genes (NCL, SEPHS2, PA2G4, SLC35G2, MYO1C, GPR158, and POU3F1) with de novo variants but unknown pathogenicity that were not previously associated with epilepsy." (PMID 34489640, 2021).
mild cognitive impairment (1 paper, 2025). "In an internal validation set including 706 mild cognitive impairment (MCI) cases and 301 controls, enhancer_CAGE, enhancer_DHS, and promoter_CAGE in the non-coding region of SEPHS2 were found to be associated with MCI (all P < 0.05)." (PMID 40728933, 2025).
Parkinson disease (1 paper, 2025). A progressive degenerative disorder of the central nervous system characterized by loss of dopamine producing neurons in the substantia nigra and the presence of Lewy bodies in the substantia nigra and locus coeruleus. "In the PhenomeXcan database, elevated transcription levels of SEPHS2 were observed in brain tissues from patients with Parkinson’s disease (PD) (P = 0.005)." (PMID 40728933, 2025).
steatosis (1 paper, 2021). Increased lipid within the cytoplasm of cells. "Of these genes, 11 coded for selenoproteins of which four genes had lower expression (SELENON, SELENOO, GPX1, and TXNRD3) and seven genes had higher expression (SELENOK, SELENOS, SELENOW, GPX2, GXP3, DIO1, and SEPHS2) in steatosis." (PMID 34869521, 2021). "Amongst the 13 genes, eight (DIO1, GPX2, SEPHS2, SELENOK, SELENOS, SELENOT, SELENOF, and SELENOW) had higher, and five (DIO3, GPX1, SELENON, SELENOO, and TXNRD3) had lower expression in steatosis." (PMID 34869521, 2021). "Four genes had lower expression in steatosis (ABCA1, MTR, MTHFR, and PLG) and five genes had higher expression (SEPHS2, DIO1, HBB, SAA1, and SAA2) in the “selenoprotein micronutrient network” pathway." (PMID 34869521, 2021). "Besides the selenoproteins GPX2, DIO1, and SEPHS2, the gene for TRNAU1AP also had higher expression in steatosis in the “selenium metabolism and selenoproteins” pathway, and TXNRD3 had lower expression in steatosis." (PMID 34869521, 2021).
cancer (20 papers, 2018 to 2025). A tumor composed of atypical neoplastic, often pleomorphic cells that invade other tissues. "This causes some cancer cells to become dependent on selenophosphate synthetase 2 (SEPHS2) to detoxify selenide." (PMID 33499222, 2021). "Selenophosphate synthetase 2 (SEPHS2), a pivotal enzyme within the selenocysteine biosynthesis pathway, is indispensable for the survival of cancer cells." (PMID 41323827, 2025). "The production of GPX4 and other selenoproteins is highly dependent on SEPHS2, and SEPHS2 has been shown to be a potential target for cancer therapy because of its important role in cancer cell survival." (PMID 41049288, 2025). "The recent finding of the prioritization GPX4, TXNRD1, and SEPHS2 synthesis in cancer cells, favoring a cell proliferative phenotype, repurposes the selenoprotein synthesis hierarchy in cancer cells." (PMID 36358931, 2022). "The selenophosphate synthetase 2 (SEPHS2), an enzyme in the selenocysteine biosynthesis pathway, is required in cancer cells to detoxify selenide, an intermediate that is formed during selenocysteine biosynthesis." (PMID 36105219, 2022). "SEPHS2 enzymes in the selenocysteine biosynthesis pathway participate in selenium detoxification in cancer cells, which is essential for the survival of cancer cells, highlighting the role of selenium metabolism in cancer." (PMID 36033459, 2022). "The strong dependence of cancer cells on Se activates detoxification mechanisms of H2Se, the end product of upstream Se metabolism, that are carried out by SEPHS2, one of the prioritized selenoproteins in these cells." (PMID 36358931, 2022). "The dependency on selenium has been described as a liability for cancer cells and proteins LRP8 and SEPHS2, which are involved in the metabolism of Sec, have been proposed as potential drug targets for cancer." (PMID 36008942, 2022). "Recently, it has been shown that selenophosphate synthetase 2 (SEPHS2) is crucial for the survival of cancer cells, because it detoxifies selenide." (PMID 34638987, 2021). "We found that the sole enzyme that processes selenide—SEPHS2—is essential in a subset of cancer cell lines, including breast cancer and glioblastoma lines, but not in any nontransformed or primary lines tested." (PMID 32709924, 2020). "These include key biological stress response genes like GPXs, TXNRD3, SELENOS, SELENOH, and the related SOD2 gene implicated in cancer cell survival, and genes such as SELENOP and SEPHS2 involved in Se biosynthesis." (PMID 30469315, 2018). "Moreover, it presents a highly promising new target and direction for the innovation of cancer treatment strategies, thereby laying a theoretical groundwork for the subsequent development of anti‐cancer drugs or therapeutic approaches targeting SEPHS2." (PMID 41323827, 2025). "Within cancer cells, apart from the xCT transporter's role in promoting selenium metabolism, there are several enzymes that influence the selenium metabolism pathway, including SEPHS2, CSE, and CBS." (PMID 41323827, 2025). "Selenide in cancer cells must be detoxed by selenophosphate synthetase 2 (SEPHS2)." (PMID 37238669, 2023). "Potentially, this implicates SEPHS2 as a “weak spot” for a cancer cell, and therapeutics targeting this enzyme may blunt cancer cell growth and development." (PMID 36358931, 2022). "This is a significant advantage, as one can easily predict which types of cancers may be amenable to SEPHS2 inhibitor treatment, either at the level of the cancer subtype or even at the individual patient level." (PMID 32709924, 2020). "Importantly, we verified a toxic gain-of-function mechanism of toxicity based on selenide toxicity, as preemptive KO of SLC7A11, while also abrogating selenoprotein production similarly to SEPHS2 KO, prevented the toxicity of SEPHS2 KO in cancer cells." (PMID 32709924, 2020). "In fact, few data are available regarding changes in SEPHS2 expression in cancer." (PMID 31695102, 2019).
cancer (continued). "SEPHS2 is a key enzyme in selenoprotein synthesis, and its essential role in cancer development warrants further investigation, particularly to pinpoint specific molecular players involved in this essentiality, their regulation, and how they may affect the metabolism of Se in cancer." (PMID 36358931, 2022). "Thus, the SLC7A11/selenide production/SEPHS2 detoxification axis illustrates a kitchen sink mechanism of toxicity, and at the same time suggests potential advantages of a metabolite poisoning strategy to kill cancer cells." (PMID 32709924, 2020). "Selenophosphate synthetase 2 (SEPHS 2) is essential for survival of cancer, but little research has focused on the role of SEPHS 1 in cancer and more functional experiments are needed." (PMID 33869278, 2021). "GPX4-mediated regulation of ferroptosis is also a survival mechanisms of cancer cells, which can increase GPX4 levels through the induction of selenophosphate synthetase 2 (SEPHS2), an enzyme involved in SeCys biosynthesis." (PMID 34948472, 2021). "Additional genes in this study, showing changes in gene expression for both the Irish and the Czech cancers were GPX2, GPX3, SELENOK, SEPHS2, SELENBP1, and SOD2." (PMID 30469315, 2018). "Indeed, the interference with SEPHS2 or SEPSECS, enzymes of the selenocysteine biosynthesis pathway, strongly impairs the lung seeding of cancer cells injected into the bloodstream." (PMID 39433871, 2024). "Selenophosphate synthetase 2, an enzyme involved in selenocysteine biosynthesis, has been found to be selectively essential for the survival of malignant cells but not in normal cells, especially in cancers that rely on GPX4 to protect cancer cells against ferroptosis such as breast cancer." (PMID 40227202, 2025).
tumor (8 papers, 2018 to 2025). "Expressions of miR-185 and that of affected genes, such as glutathione peroxidases 2 (GPX2) and selenophosphate synthetase 2 (SEPHS2), decreased considerably in tumor cells grown in selenium-deficient medium." (PMID 36287119, 2022). "Previous studies have proposed that selenite exhibits toxicity towards tumor cells and requires conversion into selenophosphate by SEPHS2, which is further transformed into the rare amino acid selenocysteine to foster cell growth." (PMID 40750759, 2025). "The depletion of SEPHS2 in tumor cells led to the accumulation of selenide, a toxic intermediate produced during SeCys biosynthesis, resulting in the inhibition of cell proliferation, loss of colony-forming ability, and cell death." (PMID 38725849, 2024). "Hence, SEPHS2 likely plays a pivotal role in maintaining the homeostasis of tumor cells, and could potentially serve as a target for cancer treatment." (PMID 40750759, 2025). "For instance, selenophosphate synthetase 2 (SEPHS2), an enzyme regulating SeCys biosynthesis, is crucial for the survival of tumor cells to detoxify Se." (PMID 38725849, 2024). "Significantly, the results of IHC staining also indicated the distinct difference of prognostic genes including SEPHS2, GPX7, and PFKFB3 between tumor and adjacent normal tissues." (PMID 37293295, 2023). "There were non-significant expression changes in the other selenoprotein genes in the TCGA, compared to significant findings in all our sample sets (SEPHS2, SELENOS), although the trend for a lower expression in tumor tissue for these genes was also seen in the TCGA." (PMID 30469315, 2018).
neurodegenerative disease (1 paper, 2025). A disorder of the central nervous system characterized by gradual and progressive loss of neural tissue and neurologic function. "Although we identified SEPHS2 and CLVS2 as SCD-related genes, we found limited evidence indicating their association with pathways influencing neurodegenerative diseases." (PMID 40728933, 2025). "Multi-omics evidence suggests that both SEPHS2 and CLVS2 may play roles in neurodegenerative diseases." (PMID 40728933, 2025).
SEPHS2 also shares sentences with these, for which no sentence is quoted: brain disorder (1 paper); colorectal tumor (1); glioblastoma (1); Hyperglycemia (1); Insulin resistance (1); leukemia (1); lymphoma (1); melanoma (1); multiple myeloma (1); neurotoxicity (1); renal carcinoma (1); Sepsis (1); triple-negative breast carcinoma (1).